NTN1 (netrin 1)
Diseases named in the same sentence as NTN1 in open-access papers (continued):
Sharing a sentence is not in itself a finding about the gene and the disease.
colorectal cancer (continued). "To further explore the specific molecular mechanism of colorectal cancer exosomal PCAT1 in the development of colorectal cancer, we cocultured exosomes with T84 cells and then transfected the cells with sh-PCAT1 or cotransfected them with sh-PCAT1 + miR-329-3p inhibitor or sh-PCAT1 + oe-Netrin-1." (PMID 36093435, 2022). "Expressing a truncated version of Netrin-1 should not pose problems for functional studies as previous publications have shown that the C-terminal domain is not necessary for receptor binding, such as to deleted in colorectal cancer (DCC)." (PMID 34342709, 2021). "First, UNC5H expression could be reduced to block the proapoptotic effect of these receptors in the absence of netrin-1, as occurs in colorectal cancer cells." (PMID 32902412, 2020). "Interestingly, colorectal carcinomas showed lowest netrin-1 levels, which is corroborated by publicly available databases on primary colorectal carcinomas (data not shown)." (PMID 24647424, 2014). "In addition, deleted in colorectal cancer (DCC), instead of neogenin-1(Neo-1) or uncoordinated (UNC5), was proved to be the specific functional receptor of Netrin-1 in regulating visceral hypersensitivity, whose upregulation may result in the most severe symptoms in the prepubertal period." (PMID 35966013, 2022). "Interestingly, NTN4 shares the laminin domain with netrin-1 (NTN1), and there is evidence that NTN4 could exert its angiogenic roles via indirect interaction with the NTN1 putative receptors Unc-5 netrin receptor B (UNC5B) and Deleted in colorectal carcinoma (DCC)." (PMID 33923095, 2021). "However, studies of human colorectal cancers have shown that only 7% of colorectal cancers have over-expression of netrin-1, implying that loss of the DCC receptor complex by 18q allelic loss or direct mutation may not confer the same selective advantage towards human colorectal cancer cells." (PMID 19424478, 2008). "Deleted in colorectal cancer and UNC5H are known as dependence receptors as they send either survival or apoptotic signals to cells dependent on the presence or absence of their ligand, netrin-1." (PMID 24720832, 2014).
atherosclerosis (30 papers, 2012 to 2025). A disease characterized by the build-up of fatty material and calcium deposition in the arterial wall resulting in partial or complete occlusion of the arterial lumen. "In another study, Bruikman and her colleagues found a genomic variant of netrin-1 leading to a familiar premature atherosclerosis." (PMID 35008701, 2021). "It has been proved in mice that deletion of Netrin-1 in myeloid cells will reduce the size and complexity of atherosclerosis lesion, and this phenomenon is associated with the emigration of macrophages from plaques." (PMID 34345249, 2021). "Netrin-1 is a recently discovered diagnostic biomarker that indicates atherosclerosis, angiogenesis, and ischemia-reperfusion damage." (PMID 32455061, 2020). "Besides, a mutation (R590L) within NTN1 is found in a family with premature atherosclerosis, strongly suggest the causative role of Netrin-1 in this common disease." (PMID 38638604, 2024). "A NTN1 mutation (R590L) is associated with a familial premature atherosclerosis." (PMID 38638604, 2024). "In contrast, subjects with a genetic mutation of Netrin-1 characterized by a reduced capacity to bind the UNC5b receptor, showed an increase in monocyte adhesion and a reduction in macrophage migration, resulting in premature atherosclerosis." (PMID 33567662, 2021). "Acetylsalicylic acid (ASS), which is usually administered to patients at increased cardiovascular risk, counteracts the inflammation-induced suppression of Ntn1 secretion by the endothelium and significantly reduces plaque sizes in a murine ApoE−/− model of atherosclerosis." (PMID 33511463, 2021). "Studies have shown that the expression of netrin-1 in the vascular lumen is higher in healthy humans, while the expression of netrin-1 in the vascular lumen is decreased in atherosclerosis." (PMID 40723793, 2025). "In atherosclerosis, for instance, netrin-1 prevents macrophage egress from plaques, thereby exacerbating lesion development." (PMID 40728980, 2025). "In contrast, macrophages with lower levels of netrin-1 showed elevated expression of the anti-inflammatory marker mannose receptor 1 (Mrc1) and the anti-atherosclerosis gene." (PMID 40723793, 2025). "When produced by circulating endothelial cells, netrin-1 has a protective effect against atherosclerosis." (PMID 40723793, 2025). "Netrin-1 is generally considered to protect atherosclerosis by inhibiting inflammation, but conflicting reports also exist." (PMID 38638604, 2024). "The Netrin-1 has already been extensively studied in other diseases such as inflammation, angiogenesis, diabetes, atherosclerosis and tumorigenesis." (PMID 38638604, 2024). "Netrin-1 plasma levels are lower in subclinical atherosclerosis and negatively correlated with plaque burden." (PMID 38638604, 2024). "Netrin-1 is also an important molecular player in atherosclerosis, exerting beneficial or disastrous effects depending on its cellular source." (PMID 38638604, 2024). "Ntn1 is described as an axon guidance molecule, which also plays an important role in atherosclerosis by regulating inflammation and the migration of immune cells such as macrophages." (PMID 36267275, 2022). "Altogether this study demonstrates for the first time that netrin-1 secreted by plaque macrophages actively promotes the progression of atherosclerosis in an Unc5b-dependent manner." (PMID 35008701, 2021). "Netrin-1, however, not only promotes the onset and propagation of atherosclerosis, but also hinders its regression." (PMID 35008701, 2021). "Our findings can be explained by the recent findings that the neuroimmune guidance cue netrin-1 contributes to maladaptive macrophage immune responses in obesity and atherosclerosis by fostering macrophage persistence in tissues." (PMID 34179515, 2021).
atherosclerosis (continued). "In a recent study, Van Gils and her colleagues showed that these macrophages, in human and murine atherosclerotic plaques, secrete a high level of netrin-1 and thereby drive the progression of atherosclerosis." (PMID 35008701, 2021). "In established atherosclerosis, cholesterol lowering alone is insufficient to promote plaque regression, as monocyte-specific netrin-1 impairs the reorganization of the plaque’s immune cell landscape and hinders monocyte egress." (PMID 35008701, 2021). "During later stages of atherosclerosis, plaque-infiltrating foam cell macrophages and VSMCs secrete Ntn1 and express the Ntn1 receptor Unc5b." (PMID 33511463, 2021). "Apart from its function acts as a signal for neuron migration, Netrin-1 can play an important role in atherosclerosis." (PMID 34345249, 2021). "It should be noted that results from van Gils's work demonstrated Netrin-1 plays a harmful role in the process of atherosclerosis, by inhibiting macrophage egress, thus, retention in the plaque, accelerating the progression of atherosclerosis." (PMID 34345249, 2021). "All these results indicate the important role of netrin-1 and its receptors in the process of atherosclerosis." (PMID 35008701, 2021). "Animal studies have shown that Netrin-1 is an important cardioprotective agent in atherosclerosis, angiogenesis, and ischemia-reperfusion injury." (PMID 32455061, 2020). "Netrin-1 and Semaphorin3E (Sema3E) have previously been demonstrated to act as deleterious retention signals for lesional macrophages thereby promoting atherosclerosis." (PMID 31035427, 2019). "Some studies have shown that an appropriate increase in the concentration of netrin-1 can alleviate myocardial ischemia-reperfusion injury and reduce atherosclerosis." (PMID 30789913, 2019). "We recently showed that the neuroimmune guidance cue netrin-1 contributes to maladaptive macrophage immune responses in obesity and atherosclerosis by fostering macrophage persistence in tissues." (PMID 31428465, 2019). "Conversely, targeted deletion of netrin-1 in macrophages, attenuates atherosclerosis in mouse models." (PMID 30532711, 2018). "A consistent result was observed in the adhesion of monocytes to endothelial cells, suggesting that netrin-1 functions as a negative regulator of atherosclerosis." (PMID 30405423, 2018). "Netrin-1 also strongly reduces leukocyte recruitment into the vascular wall in atherosclerosis, and lack or inhibition of Netrin-1 by proatherogenic factors has shown to increase leukocyte adhesion to the endothelium." (PMID 30320139, 2018). "Other evidence shows that netrin-1 promotes atherosclerosis by inhibiting the emigration of macrophages from plaques via the UNC5B receptor." (PMID 30532711, 2018). "Administration of aspirin counteracted the downregulation of netrin-1 within the vascular endothelium in a murine model of atherosclerosis, leading to a beneficial action in terms of the inflammatory plaque component." (PMID 29156815, 2017). "During atherosclerosis, plaque macrophages secrete netrin-1 to inactivate their migration via its receptor UNC5B18." (PMID 28084332, 2017). "Netrin-1 also strongly reduces leukocyte recruitment into the vascular wall in atherosclerosis and lack or inhibition of netrin-1 by proatherogenic factors have shown to increase leukocyte adhesion to the endothelium." (PMID 29059224, 2017). "In murine models of atherosclerosis, Netrin-1 was found to block macrophage movement by inhibiting actin reorganization, making cells refractory to emigration from plaques." (PMID 29445758, 2017).
atherosclerosis (continued). "Moreover, during atherosclerosis development, netrin-1 binds to Neogenin in the inner and lower smooth muscle cells (SMCs), promoting their migration to the plaques and contributing to the progression of the disease." (PMID 40723793, 2025). "In addition, research has provided potential therapeutic targets and new ideas for the treatment of atherosclerosis, including Ntn1, NOTCH, and Tcf21." (PMID 36267275, 2022). "Van Gils et al26 reported that netrin-1 might enhance atherosclerosis via suppressing foam calls’ migration to the lymph nodes, being trapped in the atherosclerotic plaques, and participating in its development and instability." (PMID 35919444, 2022). "Endothelial function in the context of atherosclerosis is essentially modulated by netrin-1 (Ntn1)." (PMID 33511463, 2021). "However, there are also studies showing Netrin-1 can make a beneficial contribution to the progression of atherosclerosis by preventing monocyte migration into the intima." (PMID 34345249, 2021). "It was shown that the deletion of netrin-1 in myeloid cells reduces atherosclerosis plaque size." (PMID 35008701, 2021). "Collectively, our data add important information about the role of Netrin-1 in the progression of atherosclerosis and suggest that its local inhibition may contribute to the reduction of plaque growth." (PMID 33567662, 2021). "However, given the dual function of netrin-1 in atherosclerosis, more insight is needed to determine at which stage of atherosclerosis netrin-1 supplementation or netrin-1 blocking substances will ameliorate atherosclerosis." (PMID 35008701, 2021). "Recent work from our group has established novel immunoregulatory roles for the neuronal guidance cues Netrin-1 and Semaphorins in guiding the immune response in the pathogenesis of cardiovascular insults such as atherosclerosis, obesity and abdominal aortic aneurysms." (PMID 31035427, 2019). "Similar to Sema3A, netrin-1 was found to be involved in the initiation of atherosclerosis." (PMID 30405423, 2018). "In the past few years, Netrin-1 has been explored to play an essential role in atherosclerosis, ischemia/reperfusion injury, and angiogenesis through involving a cardioprotective peptide, though its defined role in these disorders was protective or deleterious and has been the area of controversy." (PMID 30320139, 2018). "Therefore, we propose that CD146 promotes atherosclerosis by CD36-dependent production of retention factors including netrin-1." (PMID 28084332, 2017). "Our prior work both in vitro and in a mouse model of atherosclerosis have demonstrated that a dysfunctional endothelium markedly loses its ability to secrete netrin-1, and this compromises the integrity of the vascular barrier against inflammatory cell infiltration." (PMID 29156815, 2017). "Thus, while Netrin-1 secreted by the endothelium in the circulation explicates cardiovascular protection reducing monocyte adhesion and migration, Netrin-1 produced by macrophages within the atherosclerotic plaque contributes to atherosclerosis progression preventing macrophage egression." (PMID 33567662, 2021). "This discrepancy may be attributed to the stage of atherosclerosis Netrin-1 exerting effects." (PMID 34345249, 2021). "Interestingly, fatty liver status shared several pathways also associated with atherosclerosis or atherothrombosis (CD40/CD40L signaling pathway, Netrin-1 signaling and pathways contributing to thrombosis) i.e., another lipid related condition where lipids are accumulated to artery wall." (PMID 29985430, 2018). "Bone marrow transplantation of Ntn1−/− cells into LDL−/− mice, which develop atherosclerosis on a high-fat diet, decreased plaque size development by 45%." (PMID 35008701, 2021).
atherosclerosis (continued). "Since Netrin-1 exerts chemorepulsive effects (through interactions with Unc5B) or chemoattractive effects (through interactions with either DCC or neogenin), the specific contributions of Netrin-1 in atherosclerosis are of interest." (PMID 30283356, 2018). "Furthermore, the increased expression of macrophage-derived netrin-1 in the vessel wall of atherosclerosis (AS) prevents the outflow of foam cells, which, unlike netrin-1 from endothelial cells, exacerbates the condition." (PMID 40723793, 2025).
Obesity (22 papers, 2015 to 2026). Accumulation of substantial excess body fat. "In murine models of obesity, the overexpression of netrin-1 in adipose tissue macrophages is associated with impaired emigration, enhanced tissue inflammation, which leads to an increased insulin resistance." (PMID 40949120, 2025). "The involvement of NTN-1 in the regulation of obesity-associated pathologies has been extensively demonstrated." (PMID 36831381, 2023). "To decipher the mechanisms underlying CC development during obesity, we examined the expression of NTN1 and its receptors in the visceral adipose tissue (VAT) of 74 (25 normal weight (NW)) (16 with CC) and 49 patients with OB (12 with CC)." (PMID 36831381, 2023). "Further studies in larger cohorts will shed light on our understanding of the role of NTN-1 in obesity-associated CC." (PMID 36831381, 2023). "Netrin-1 (NTN-1) regulates obesity-associated low-grade inflammation, being also involved in the control of cell migration and proliferation." (PMID 36831381, 2023). "Although NTN-1 plays crucial functions in inflammatory diseases, little is known about its regulation and roles in the obesity-associated VAT inflammation." (PMID 36297056, 2022). "Consistent to our results, loss of Ntn1 expression in AT macrophages lead to improved maintenance of glucose homeostasis and insulin sensitivity during obesity." (PMID 36297056, 2022). "We aimed to determine the impact of NTN-1 on obesity and obesity-associated type 2 diabetes, as well as its role in visceral adipose tissue (VAT) inflammation." (PMID 36297056, 2022). "Increased (p < 0.001) circulating concentrations of NTN-1 in obesity decreased (p < 0.05) after diet-induced weight loss being also associated with a reduction in glucose (p < 0.01) and insulin levels (p < 0.05)." (PMID 36297056, 2022). "Our data suggest that increased circulating NTN-1 levels in obesity decrease after diet-induced weight loss being also associated with a reduction in IR." (PMID 36297056, 2022). "Further in depth analyses of VAT macrophage subpopulations using single cell RNA-seq showed that deficiency of netrin-1 specifically reduced resident and Lcn-hi macrophage subsets, while the major macrophage population in obesity was expanded." (PMID 31428465, 2019). "We show herein that loss of macrophage netrin-1 expression in mice (Ntn1Δmac) reduces the inflammation and insulin resistance associated with diet-induced obesity." (PMID 31428465, 2019). "For this purpose, tubular injury biomarkers, such as kidney injury molecule-1 (KIM-1), N-acetyl-β-D-glucosaminidase (NAG), neutrophil gelatinase-associated lipocalin (NGAL), and netrin-1, were recently investigated in patients with obesity." (PMID 30035656, 2018). "Investigating concordance between serum Netrin-1 and its expression in adipose tissue could provide critical insights into its role in obesity-associated inflammation." (PMID 40949120, 2025). "We hypothesised that dysfunctional visceral AT (VAT) in patients with obesity is associated with increased NTN1 expression levels promoting an inflammatory microenvironment that favours CC development." (PMID 36831381, 2023). "Furthermore, macrophage deficiency of netrin-1 altered the fate and functional trajectory of ATMs in obesity, with the major macrophage subpopulation showing increased expression of genes involved in migration, lipolysis and fatty transport." (PMID 31428465, 2019). "We aim to study whether excess visceral adipose tissue in patients with obesity and colon cancer is associated with increased NTN1 and the expression levels of its main receptors, promoting an inflammatory microenvironment that favours colon cancer development." (PMID 36831381, 2023). "Moreover, the increased circulating levels of NTN-1 in obesity were associated with IR and the decrease of NTN-1 after caloric restriction was positively correlated with differences in glucose and insulin levels, suggesting the role of NTN-1 in the development of IR." (PMID 36297056, 2022).